TIMM10B (translocase of inner mitochondrial membrane 10B)
Description:
Component of the TIM22 complex, a complex that mediates the import and insertion of multi-pass transmembrane proteins into the mitochondrial inner membrane. The TIM22 complex forms a twin-pore translocase that uses the membrane potential as the external driving force. In the TIM22 complex, it may act as a docking point for the soluble 70 kDa complex that guides the target proteins in transit through the aqueous mitochondrial intermembrane space.
Synonyms: Tim10b; FXC1; TIM9B
Tractability: Small molecule: a structure with a bound ligand is known. Antibody: UniProt places it where antibodies can reach, with high confidence. PROTAC: ubiquitination databases record sites on it; its protein half-life has been measured.
Gene: Protein-coding gene on chromosome 11 (6,481,496 to 6,484,683, forward strand). Ensembl gene ENSG00000132286.
Subcellular location: Mitochondrion inner membrane
Pathways (Reactome):
Protein localization: Mitochondrial protein import
Gene Ontology:
Molecular function: protein binding; protein transporter activity
Biological process: protein insertion into mitochondrial inner membrane
Cellular component: mitochondrial inner membrane; mitochondrial intermembrane space; mitochondrial intermembrane space chaperone complex; mitochondrion; TIM22 mitochondrial import inner membrane insertion complex
Genetic constraint (gnomAD): Loss-of-function variants: 21 observed, 15.4 expected, observed/expected ratio (o/e) 1.36, 90% interval 0.96 to 1.85. The upper end of that interval is the gene's LOEUF score, 1.85, which puts it in group 6 of 6, group 1 being the genes least tolerant of losing a copy. Missense variants: 165 observed, 136.09 expected, observed/expected ratio (o/e) 1.21, 90% interval 1.07 to 1.38. Synonymous variants: 63 observed, 53.64 expected, observed/expected ratio (o/e) 1.17, 90% interval 0.96 to 1.45.
Homologues: Orthologues: chimpanzee TIMM10B (99% identical), pig TIMM10B (97% identical), dog TIMM10B (96% identical), macaque TIMM10B (96% identical), rabbit TIMM10B (91% identical), rat Timm10b (89% identical), mouse Timm10b (88% identical), guinea pig TIMM10B (82% identical), tropical clawed frog timm10b (57% identical), zebrafish timm10b (51% identical), Drosophila melanogaster Tim9b (29% identical).
Diseases named in the same sentence as TIMM10B in open-access papers:
TIMM10B is named in the same sentence as 3 diseases in open-access papers, as found by Europe PMC text mining. Sharing a sentence is not in itself a finding about the gene and the disease.
TIMM10B shares sentences with these, for which no sentence is quoted: COVID-19 (1 paper); Mohr-Tranebjaerg syndrome (1); steatosis (1).